LIN28B (lin-28 RNA binding posttranscriptional regulator B)
Diseases named in the same sentence as LIN28B in open-access papers (continued):
Sharing a sentence is not in itself a finding about the gene and the disease.
cancer (continued). "In addition, genes whose expression was suppressed by BA included ID1, which is associated with regulation of CSCs and treatment resistance; SRSF1, which contributes to RNA splicing that alters cancer stem cell plasticity; and LIN28B, an oncogenic stem cell factor involved in EMT." (PMID 40316727, 2025). "Inflammation is an established driver of many cancers including those of the liver and NF-κB has been shown to promote HCC in the setting of cholestatic-induced liver injury akin to that seen in ΔS6 livers as well as in the setting of Rpl22-deficiency via induction of the pluripotency factor Lin28b." (PMID 36656901, 2023). "In addition to tumor initiation, LIN28B is necessary for the maintenance of cancers as well." (PMID 33575478, 2021). "Thus, regulation of LIN28B/let-7 balance is one important driver in cancer development." (PMID 31484926, 2019). "Therefore, the oncogenic function of LIN28B may be context-dependent and cancer-type-specific, that is, the outcome of LIN28B reactivation in cancers largely depends on the existing cellular mRNA and miRNA transcriptome in different cancer patients." (PMID 30174831, 2018). "Thus, given that LIN28B has a significant role in CSCs, it can serve as a vital target for eradication of CSCs, which are thought to be the origin of tumor resistance, recurrence, and metastasis of cancer." (PMID 28693523, 2017). "In addition, an analysis of Lin28 and Lin28B expression in various cancers suggested that Lin28B may be the more relevant homologue in tumorigenesis." (PMID 28947981, 2017). "Of note, under certain conditions, LIN28A/LIN28B may also inhibit cancer cell proliferation." (PMID 26123544, 2015). "Therefore, to investigate whether Lin28B is expressed in cancer stem cells, we performed magnetic cell sorting (MCS) to separate HCC cell lines into EpCAM+ and EpCAM- populations." (PMID 24244607, 2013). "Since Lin28B is a candidate oncofetal gene which is possibly related to stem cell phenotypes, it is a potential surrogate tumor marker to detect circulating cancer stem cells which have been shown to have highly predictive value for cancer recurrence and metastasis." (PMID 24244607, 2013). "As expected, overexpression of LIN28B and IGFBP1-3 was able to genetically rescue cancer initiation." (PMID 38875287, 2024). "Another important set of genes that drive the ncRNA-influenced development of embryonic cells and cancer cells includes LIN28A and LIN28B." (PMID 36980876, 2023). "We chose 9 genes that were downregulated in LINC02159-knockdown NSCLC cells, including HMGA2, LIN28B, and YAP1, among others, as these genes have been demonstrated to be essential for cancer development and progression." (PMID 37537569, 2023). "LIN28B is an oncofetal RBP, with high expression during early embryogenesis, low expression in differentiation and adult tissues, and over-expression in cancer cells." (PMID 36307883, 2022). "Previous studies have shown that co-expression of LIN28B and ALDH1 isoform was significantly found in cancer stem-like cells and tumor tissues." (PMID 34837926, 2021). "In particular, HMGA2, LIN28B, and IGF2BP1 have been referred to as an “oncogenic triangle” that is critical for cancer initiation and that was also co-ordinately overrepresented in our data." (PMID 34706236, 2021). "In NB, elevated LIN28B expression levels inhibits let-7 with consequent de-repression of MYCN that reinforces cancer cell proliferation, activating the feedback loops of the MYCN-LIN28B axis." (PMID 34771690, 2021).
cancer (continued). "In these five cancers, IGF2BP1 followed by LIN28B were the in average most upregulated mRNA-binding proteins (mRBPs) among 660 detected and reported by the RBP census." (PMID 32761127, 2020). "To search for the origin of LIN28B-expressing cancer cells within primary PDAC tumors, we analyzed an independent cohort of 80 resected PDAC tumors for LIN28B RNA expression by RNA in situ hybridization and at the protein level by immunohistochemistry." (PMID 32620742, 2020). "On the contrary, let-7 has target genes [HMGA2 (High Mobility Group AT-Hook 2), IMP-1 (IGF2 mRNA-binding protein 1), LIN28B (Lin-28 homolog B), Ras, and MYC) important for cancer cell stemness." (PMID 32150871, 2020). "Curcumin, a natural anti-cancer agent, increased the sensitivity of HCC cells to paclitaxel through inhibiting NF-κB stimulated Lin28B expression both in vitro and in vivo." (PMID 31762817, 2019). "In cancer cells, the embryonic function of LIN28A/LIN28B is subverted to induce a metabolic shift from oxidative phosphorylation to glycolysis." (PMID 28400788, 2017). "Lin28B immunoreactivity was predominantly observed in the cytoplasm of PDAC cells, although nuclear staining was also observed in some cancer cells." (PMID 28947981, 2017). "Let‐7i is a member of the let‐7 family of tumor suppressor miRNAs that inhibits cancer cell proliferation, survival, migration, and invasion by downregulating a variety of oncogenes such as myc, Ras, HMGA2, and Lin28B." (PMID 28079973, 2017). "In cases where a specific cancer type expresses both LIN28A and LIN28B, these tend to occur in distinct tumor subtypes." (PMID 28400788, 2017). "TRIM71 is the most-upstream post-transcriptional modulator in the Lin28B-let-7-HMGA2 oncogenic signaling pathway, and serves a pivotal role in tumor formation, tumorigenic progression, and malignancy of cancer." (PMID 27821801, 2016). "Second, we extended this analysis beyond primary cells, introducing siRNA specific for TRIM71 in the cancer cell lines Caco-2 and Tera-1, which express both TRIM71 and Lin28B as well as all components of the conserved signaling pathway." (PMID 27821801, 2016). "Since myc is one of the target genes of let-7, let-7-mediated inhibition of myc thus inhibits the crosstalk of hallmarks of cancers; LIN28A/LIN28B, of course, has the opposite effect." (PMID 26123544, 2015). "Thus, Lin28B may play a certain role in inducing or maintaining cancer stem cell phenotypes." (PMID 24244607, 2013). "Just because LIN28B promoted global protein synthesis rates does not mean that this is the means through which cancer initiation is promoted." (PMID 38875287, 2024). "Although neither LIN28A nor LIN28B are usually present in mature tissues, they are re-expressed in several cancers to support cancer growth." (PMID 38976670, 2024). "LIN28B was upregulated during redifferentiation, leading to the suppression of the let-7 miRNA and, finally, the HMGA2-mediated upregulation of SOX2, resulting in the formation of a cancer stem-cell-like phenotype and the development of t-NEPC." (PMID 37304235, 2023). "In cancer, TGF-β-mediated activation of LIN28B has been reported in PDAC." (PMID 34548635, 2022).
cancer (continued). "In this way, the LIN28/Let-7 pathway operates in a double negative feedback loop and overexpression of LIN28A or LIN28B is correlated with cancer progression in several different cancer types including liver, breast, and lung." (PMID 33572600, 2021). "Lin28B participates in the EMT and represses the biogenesis of let-7, which may be one of the molecular mechanisms by which Lin28B promotes cancer progression and metastasis." (PMID 28947981, 2017). "LIN28B positive staining was identified in nucleus or both nucleus and cytoplasm in cancer specimens, whereas weak or negative staining was detected in the normal counterparts." (PMID 26478718, 2015). "As discussed, the expression patterns and functions of LIN28A/LIN28B and let-7 in malignancies are largely opposing and appear to compose a double-negative feedback loop regulating cancer progression." (PMID 26123544, 2015). "In this review, we summarized the mechanisms of LIN28A/LIN28B and let-7 loop aberrant regulation in human cancer and discussed the roles and potential mechanisms of the LIN28A/LIN28B and let-7 loop in regulating the hallmarks of cancer." (PMID 26123544, 2015). "The link between targeting LIN28B and its involvement in tumour initiation, stemness, growth, metabolism, resistance to therapy, recurrence, and metastasis has been widely reported for other cancer types but not for MB." (PMID 40265419, 2025). "This suggests that while LIN28B may not alone be sufficient for tumor establishment, it does play an important role in cancer growth." (PMID 37341142, 2023). "Interestingly, TRIM71 expression is downregulated in various cancer tissues in which the LIN28B–let-7–HMGA2 signaling pathway is conserved compared with normal tissue counterparts." (PMID 35806250, 2022). "Notably, these elevated cancer -promoting inflammatory cytokinesare regulated by STAT3 pathway, indicating that LIN28B possibly promotes malignant cholangiocytes transformation by inducing the expression of tumor -promoting inflammatory cytokines via STAT3 signaling pathway." (PMID 34837926, 2021). "We anticipate that therapeutic targeting of the LIN28B/let-7 pathway will not be limited to PDAC and that targeting LIN28B pathway activation might impact the metastatic potential of a broad range of cancers." (PMID 32620742, 2020). "In addition, Lin28B silencing in PDAC cells inhibited cell proliferation, cell cycle transition, migration and the EMT and increased the expression of the c-MYC, HMGA2 and KRAS genes, which are targeted by the cancer suppressor miRNA let-7." (PMID 28947981, 2017). "Since Lin28B and HMGA2 are downstream post-transcriptional targets of TRIM71, we co-overexpressed Lin28B or HMGA2 with TRIM71 to determine whether Lin28B or HMGA2 overexpression overcomes the inhibitory effect of TRIM71 on tumorigenic phenotypes (proliferation and invasion) of cancer cells." (PMID 27821801, 2016). "The stemness gene LIN28B promotes cancer stemness and metastatic properties by enhancing glycolysis and lactate secretion, partly through modulating the MYC/miR-34a signaling pathway, suggesting that miR-34a may regulate CSCs through rewiring cancer metabolism." (PMID 33763422, 2021). "In addition, DENSpm-treated cells exhibited elevated levels of expression of several key stem cell markers including POU5F1, Sox9, CD44, BMI1, and Lin28B, although other transcripts that are found in liver stem and cancer stem cells remained absent (PROM1, CD133)." (PMID 30567412, 2018). "To confirm that our Lin28 inhibitors can block Lin28A activity in cancer cells, we have used the IGROV1 cell model that expresses Lin28A but not Lin28B protein." (PMID 36428779, 2022). "For many cancers that appear not to express LIN28AB in the tumor, the CSC population is LIN28A or LIN28B positive." (PMID 28400788, 2017).
cancer (continued). "The absence of SIRT6 leads to hyperacetylation of the Lin28b promoter, Myc recruitment, and significant induction of Lin28b and its downstream let-7 target genes IGF2BP1, IGF2BP3, and HMGA2, thereby promoting the development of cancer." (PMID 35463332, 2022).
tumor (160 papers, 2010 to 2026). "More specific to CRC, LIN28B expression is associated with colorectal tumorigenesis, tumor growth, cell migration, and tumor recurrence." (PMID 37318881, 2023). "Overexpression of LIN28A or LIN28B is associated with a variety of tumors, leading to increased tumor aggressiveness and poorer prognosis." (PMID 36831493, 2023). "Therewith, LIN28B was identified to be associated with OSCC tumor size, advanced clinical stage, shorter disease-free survival, and lower overall survival in clinic." (PMID 34353342, 2021). "The loss of SIRT6 in PDAC tumor models was associated with upregulation of LIN28B and consequently increased expression of the let-7 targets HMGA2, IGF2BP1, and IGF2BP3." (PMID 32545414, 2020). "LIN28B expression is associated with tumor initiation, progression, resistance, and poor outcomes in several solid cancers, including ovarian cancer." (PMID 30154460, 2018). "Overexpression of LIN28A/LIN28B is related with advanced disease stage among multiple tumor types and typically associates with poor prognosis." (PMID 28400788, 2017). "Transcriptional activation of Lin28B is closely associated with interactions of the Myc transcription factor with E-boxes in the Lin28B promoter in tumor models." (PMID 27821801, 2016). "We found that the detection of circulating Lin28B is also associated with high tumor grade, large tumor size and high AJCC stage and BCLC stage." (PMID 24244607, 2013). "In HCC patients, circulating Lin28B was associated with high tumor grade (P=0.046), large size (P=0.005), high AJCC stage (P=0.044) and BCLC stage (P=0.017)." (PMID 24244607, 2013). "While the expression of Lin28b has been linked to advanced tumor stage, the precise molecular mechanism(s) by which Lin28b drives disease progression is still being unraveled." (PMID 23482325, 2012). "However, the underlying molecular mechanisms of LIN28B-driven EC pathogenesis and its potential immunomodulatory functions within the tumor microenvironment remain poorly characterized." (PMID 40740861, 2025). "Furthermore, a high expression of LIN28B in NB is associated with a poor prognosis, an aggressive disease phenotype, and the promotion of tumor cell migration and survival." (PMID 38732012, 2024). "In conclusion, LIN28A and its paralog LIN28B are RBPs closely associated with tumors, and they exert their biological function by inhibiting the biosynthesis of members of the tumor suppressor gene let-7 miRNA family or changing the translation efficiency of the mRNA they bind." (PMID 36831493, 2023). "Similar data were seen in human PDAC, as CM from PANC-1, PANC03.27 and hPDAC1# induced LIN28B expression in human CAFs (hCAFs) in a LIN28B-‍dependent manner, confirming that loss of Lin28b in tumor epithelium leads to the inactivation of Lin28b in CAFs in both human and murine PDAC." (PMID 37898598, 2023). "However, the underlying molecular mechanisms of how LIN28B functions in tumor metastasis, especially in CRC, are unclear and require elucidation for potential translational therapeutics." (PMID 37318881, 2023). "Upregulation of LIN28B in NB blocks let-7 precursors from being processed to mature let-7 miRNAs and shows genomic aberrations and extensive overexpression in high-risk NBs compared to several other tumor entities and normal tissues." (PMID 34771690, 2021). "Finally, knock-down or conditional silencing of LIN28B in these Myc-driven models was associated with reduced tumor burden and prolonged survival of animal models, supporting a role of Lin28B in tumor maintenance." (PMID 31979130, 2020). "Based on previous reports, we speculated that the AURKA rs8173 might reduce the risk of WT by inhibiting the proliferation and migration of tumor cells through the LIN28B-RAN-AURKA-MYCN signaling pathway." (PMID 31636670, 2019).
tumor (continued). "The association between merlin and Lin28B is induced when merlin is dephosphorylated, which occurs at high cell density, suggesting a novel mechanism in which merlin exerts cell-density-dependent tumor suppression through let-7 miRNA maturation." (PMID 29587439, 2018). "Notably, LIN28B abundance was found to be associated with tumor size and cervical lymph nodes metastasis with P value 0.049, 0.0286, respectively." (PMID 26478718, 2015). "Finally, in a cohort of 38 HNSCC patient tumour samples, over-expression of Lin28b, IGF2BP2, and IGF2 were observed to be associated with worse clinical outcome, strongly suggesting a role for the Lin28b-IGF pathway in contributing to HNSCC relapse." (PMID 23482325, 2012). "Notably, LIN28B expression was associated with advanced tumor grade and poor prognosis." (PMID 37898598, 2023). "However, Lin28B expression was associated with clinical tumor grade and distal metastasis." (PMID 35173168, 2022). "Notably, the authors could show that Lin28B abundance was associated with tumor size as well as cervical lymph nodes metastasis." (PMID 32957697, 2020). "LIN28B enhances therapeutic resistance and tumor recurrence by potentiating proliferation and epithelial-mesenchymal transition, positioning it as both a predictive biomarker and therapeutic target." (PMID 40740861, 2025). "While the RNA-binding protein LIN28B has been reported to promote the progression of EC, its mechanistic role in driving tumor progression and immune modulation remains poorly characterized." (PMID 40740861, 2025). "LIN28B exhibits oncogenic roles in EC by facilitating MYC-mediated tumor progression and modulating the immune microenvironment, establishing its potential as both a therapeutic target and a prognostic biomarker." (PMID 40740861, 2025). "To further examine the effect of MYC on modulating the tumor-promoting activities of LIN28B in EC, we performed transwell assays." (PMID 40740861, 2025). "Our study reveals that LIN28B drives EC progression through MYC-mediated oncogenesis while concurrently shaping an immunosuppressive tumor microenvironment." (PMID 40740861, 2025). "LIN28B, on the other hand, promotes stem cell self-renewal and tumor metastasis by inhibiting members of the let-7 miRNA family." (PMID 41446875, 2025). "The forest plot revealed that several factors, including LIN28B expression, histological type, clinical stage, age, histological grade, and residual tumor, were significant predictors of survival in EC patients." (PMID 40740861, 2025). "In some tumor cells, Lin28a and Lin28b regulated Pdk1 through let-7g to promote glycolysis and inhibit PDH activity." (PMID 39858120, 2025). "LIN28b enhances aerobic glycolysis and lactate secretion in tumor cells via the LIN28b/MYC/miR-34a pathway." (PMID 40384875, 2025). "LIN28B has been demonstrated to correlate with tumor immune escape, as well as the immune microenvironment." (PMID 40740861, 2025). "LIN28B is widely recognized for its oncogenic properties, demonstrating aberrantly elevated expression levels across multiple tumor types." (PMID 40740861, 2025). "Analysis of LIN28B expression in paired tumor and normal tissues (n=23) from the TCGA database revealed a significant upregulation of LIN28B expression in tumor tissues." (PMID 40740861, 2025). "One key example is represented by the developmental gene LIN28B, whose aberrant reactivation in adult tissues promotes tumor initiation and progression." (PMID 38704454, 2024). "Based on our observations, we propose a general model in which SOX6 acts as a tumor suppressor in cells of different tissue origin acting through the LIN28B/Let-7 pathway." (PMID 38704454, 2024). "We therefore utilized immunohistochemistry to analyze tumor structure (H&E), cell division (Ki67), cellular senescence (p16ink4a), cell death (cleaved caspase 3), as well as LIN28B." (PMID 38686627, 2024).